SNORA70 (Small nucleolar RNA SNORA70 )
Synonyms: LOC124900346
Gene: Small nucleolar RNA gene on chromosome 14 (51,244,090 to 51,244,224, forward strand). Ensembl gene ENSG00000201376.
Gene Ontology:
Biological process: RNA processing
Cellular component: nucleolus
Homologues: Orthologues: chimpanzee SNORA70 (93% identical), macaque SNORA70 (93% identical), guinea pig SNORA70 (69% identical), guinea pig SNORA70 (68% identical), guinea pig SNORA70 (67% identical), guinea pig SNORA70 (66% identical), guinea pig SNORA70 (65% identical), guinea pig SNORA70 (64% identical), guinea pig SNORA70 (63% identical), guinea pig SNORA70 (62% identical), guinea pig SNORA70 (58% identical), guinea pig SNORA70 (56% identical), and 2 more. Paralogues in human: SNORA70H (73% identical), SNORA70 (72% identical), SNORA70 (71% identical), SNORA70B (70% identical), SNORA70C (70% identical), SNORA70G (70% identical), SNORA70 (70% identical), SNORA70I (70% identical), SNORA70J (70% identical), SNORA70 (68% identical), SNORA70E (68% identical), SNORA70F (67% identical), and 14 more.